GSTP1 (glutathione S-transferase pi 1)
Diseases named in the same sentence as GSTP1 in open-access papers (continued):
Sharing a sentence is not in itself a finding about the gene and the disease.
cancer (continued). "GSTP1 is often overexpressed in cancers such as lung, breast, and prostate, where it has been linked to chemotherapy resistance." (PMID 39954068, 2025). "Telcyta (TLK-286) is an GSH analog that is used together with platinum, taxane, and anthracycline cytotoxic chemotherapies in a range of cancers that express very high levels of the glutathione S-transferase pi-1 gene (GST-P1-1)." (PMID 38256132, 2024). "A meta-analysis conducted in 2023 showed that the GSTP1 rs1695 polymorphism was significantly correlated with platinum-induced toxicities; it was concluded that personalized chemotherapy based on these polymorphisms could be considered for cancer patients in the future." (PMID 39125992, 2024). "In contrast, other glutathione-related enzymes, such as GSTO1 (Glutathione S-Transferase Omega 1) and GSTP1 (Glutathione S-Transferase Pi 1), exhibited distinct expression patterns across different cancers, pointing to complex regulatory mechanisms at play." (PMID 39594421, 2024). "Overexpression of GSTs, particularly GSTP1-1, is often considered to be a mechanism of cancer drug resistance." (PMID 39125992, 2024). "The GSTP1 gene is preceded by a large CpG-rich region that is frequently affected by methylation during cancer." (PMID 39684755, 2024). "Given the importance of GSTP1 in cell biology, cancer and multiple other pathologies, further study of GSTP1 palmitoylation is warranted." (PMID 39269939, 2024). "When cancer cells are exposed to paclitaxel, GSTP1 plays a crucial role in DR by capturing and detoxifying paclitaxel within the cells." (PMID 38686048, 2024). "Leveraging SMURF2 to selectively degrade GSTP1 provides a promising approach for driving ferroptosis in cancer cells resistant to conventional therapies." (PMID 39697237, 2024). "The degradation of GSTP1 by SMURF2 not only diminishes the cell’s ferroptotic defenses but also sensitizes cancer cells to treatments that induce ferroptosis." (PMID 39697237, 2024). "Epigenetic modifications in the GSTP1 gene can be recognized as biomarkers for the diagnosis of cancer in its early stages and, thus, for prophylaxis or treatment monitoring." (PMID 39125992, 2024). "Due to its role in chemoresistance, GSTP1 is by far the most extensively investigated glutathione transferase in cancers." (PMID 38674199, 2024). "GSTP1 is the most studied GST isoform in different types of cancer, which has the potential to regulate AMPK/mTOR and MAPK signaling and facilitate protein synthesis and cell proliferation, respectively." (PMID 39044272, 2024). "Considering this role, we aimed to investigate GSTT1, GSTM1 and GSTP1 characterised polymorphic markers in a mixed cohort of cancer patients receiving chemotherapy." (PMID 36939926, 2023). "GSTP1 is an enzyme intimately involved in resistance to anti-cancer drugs, and its inhibitor NBDHEX can suppress the catalytic activity and prevent it from interacting with signaling molecule(s)." (PMID 37491277, 2023). "Another GST, GSTP1, increased autocrine growth on cancers with Kirsten rat sarcoma viral oncogene homologue (KRAS) and B-raf proto-oncogene serine/threonine kinase (BRAF) mutations." (PMID 36978808, 2023). "A major tissue biomarker, GSTP1, is effective in detecting a variety of cancers, including PCa, breast, lung, and HCC." (PMID 37901797, 2023). "CAT and GSTP1 genetic variability was thoroughly studied in oxidative-stress-related diseases, especially different types of cancer, while in neurodegeneration, NFE2L2 and KEAP1 have recently gained the interest of researchers." (PMID 36829875, 2023). "In NSCLC patients, the frequency of GSTP1 methylation in cancer tissues ranges from 0 to 25%, while neighboring benign tissues show less or no methylation." (PMID 37901797, 2023). "Epigenetic modifications in the GSTP1 gene can be recognised as biomarkers for the diagnosis of cancers in its early stages, and thus for prophylaxis or treatment monitoring." (PMID 37819495, 2023).
cancer (continued). "NBDHEX (6-(7-nitro-2,1,3-benzoxadiazol-4-ylthio) hexanol) is another inhibitor of GSTP1-1 and other GSTs that has shown anti-proliferative activities in various cancer cells." (PMID 37189435, 2023). "Among the known isoenzymes of GST, the most studied polymorphisms in relation to cancers are the SNP in the GSTM1, GSTT1 and GSTP1 genes." (PMID 37819495, 2023). "On the other hand, several studies evidenced that certain polymorphisms occurring within the GSTP1 gene, modulate the risk of developing ESRD and BEN-associated carcinoma." (PMID 37629712, 2023). "The most significant DMRs associated with gene expression changes, include several cancer-related genes such as KLF10, GSTP1, MEGF10, SOX8 and IRX116–28." (PMID 34997020, 2022). "GSTP1 is crucial for the metabolism of cisplatin in vivo and reduces sensitivity of cancer cells to etoposide." (PMID 36362093, 2022). "There are various types of GSTs, among which Pi class GST (GSTP1) is highly expressed in various cancers and contributes significantly to the acquisition of drug resistance in cancer cells." (PMID 36611862, 2022). "Prominent members of the GST family, such as GST pi 1 (GSTP1), tend to be highly expressed in various cancers." (PMID 36291099, 2022). "Expression levels of GSTP1 were further validated with immunofluorescence staining, confirming the confinement of GSTP1 expression to cancer nests." (PMID 35776767, 2022). "By contrast to silencing GSTP1, an induction of expression of GSTP1 protein is used to detect early cancer formation in response to carcinogenic exposure in the rat liver." (PMID 34191807, 2021). "They reported that cell cycle progression was unaffected; however, cell invasion and migration were significantly reduced in GSTP1 knockdown cancer cells." (PMID 33946704, 2021). "Glutathione S-transferase pi 1 (GSTP1) is a phase II metabolic enzyme involved in the detoxification of various anti-cancer drugs and other carcinogens." (PMID 33995103, 2021). "We then investigated the association of GSTP1 and GSTM2 promoter methylation with the TMB and CNA burdens and expression of the proliferation marker Ki-67 in all other cancer types from TCGA." (PMID 34871444, 2021). "Further, the percentages of tumors from Black patients who had all TMA spots with cancer cells staining positive for GSTP1 (9.5%) was 3-fold higher than the percentage of tumors from White patients (3.2%; P<0.001)." (PMID 34191807, 2021). "Convincing data suggest inhibiting GSTP1 protein levels and activity can increase oxidative stress, impair cancer-cell survival, reduce chemoresistance, and improve overall survival in patients." (PMID 33946704, 2021). "Overall, 7.7% of cases contained GSTP1 positive cancer cells in a subset of TMA cores, and 4.5% had GSTP1 positive cancer cells in all TMA cores." (PMID 34191807, 2021). "When not considering race, the percentage of cases with any TMA spot or all TMA spots with cancer cells staining positive for GSTP1 was lower in those who were ERG+ than ERG-." (PMID 34191807, 2021). "GSTP1 acts as a homodimer to catalyze reactions between reactive oxygen species, anti-cancer drugs or carcinogens, and glutathione, sometimes ‘detoxifying’ and at other times ‘toxifying’ the substrates." (PMID 34191807, 2021). "The percentage of patients with ERG positive cancers that were also GSTP1 positive was 23.1% in Black men, but only 5.1% in White men, a difference that was statistically significant (P = 0.001)." (PMID 34191807, 2021). "Active research in the field of antioxidants and redox biology has narrowed to GSTP1 as a promising therapeutic target for cancer treatment." (PMID 33946704, 2021). "In cancer, GSTP1 has been found to be a tumor suppressor or oncogene, depending upon the tumor of interest." (PMID 34669463, 2021).
cancer (continued). "Hypermethylation of the GSTP1, a tumor suppressor gene, frequently occurs in different cancer types, including PCa." (PMID 35053153, 2021). "In mouse models of carcinogen exposure induced cancers of the lung and skin, Gstp1/2 behaves as a tumor suppressor." (PMID 34191807, 2021). "Regarding metastatic PCa, both RASSF1A and GSTP1 exhibited pathological DNA methylation levels in all PCa patients, supporting beneficial application of this epigenetic biomarker analysis for cancer therapy control and early detection of metastasis." (PMID 34503269, 2021). "When considering its role in cancer metabolism, in addition to detoxification of potential cancerogenic substances, GSTP1 is capable of increasing drug efflux from the cell thus contributing to chemoresistance." (PMID 33953831, 2021). "GSTP1 expression was increased in EVs from 5-fluorouracil or adriamycin resistant cancer cell lines (Yang S.-J." (PMID 33995103, 2021). "As a proof of concept, we targeted loci in healthy donor DNA, including a highly variable hexanucleotide repeat in C9orf72, and four cancer-related genes with guide RNAs previously validated for PCR-free targeted sequencing (GSTP1, KRT19, GPX1, SLC12A4)." (PMID 33830997, 2021). "Five core ADME genes coding for phase II drug metabolism enzymes showed significant associations of their intratumoral expression levels with OS rates in cancers, including GSTP1, NAT1, UGT1A1, UGT2B15, UGT2B7." (PMID 33202946, 2020). "Knocking down GSTP1 in cancer cells significantly decreases cell proliferation, while early apoptosis occurs." (PMID 33087132, 2020). "With this rational in view, validation of the present in silico observations was sought to be done by quantifying the level of 8-OHdG in DNA digests of cancer cells obtained from patients with different GSTP1 genotypes." (PMID 32265484, 2020). "Conversely, overexpression NQO1 and GSTP1 promote cancer cell proliferation, supporting that higher NQO1 and GSTP1 levels are essential for cancer cell proliferation and the redox homeostasis." (PMID 33087132, 2020). "Many human cancers have been shown to express high levels of GSTP1-1 and their expression has been correlated with both disease progression and chemotherapy resistance." (PMID 33215267, 2020). "These, and additional literature, suggest that GSTP1 plays versatile roles in cancer cell survival, signaling mechanisms, and metabolism." (PMID 32526885, 2020). "Regarding GSTP1 polymorphisms, whose gene is located on chromosome 11 (11q13.2), two commonly occurring polymorphisms within the exon 5/6 region of the gene (rs1695 c.313A > G, p.IIe105Val and rs1138272 c.341C > T, p.Ala114Val) may be related to the occurrence and development of various cancers." (PMID 32183092, 2020). "More recently a six-gene methylation panel has been developed, termed ‘Epigenetic Cancer of the Prostate Test in Urine’ (epiCaPture), which targets GSTP1, SFRP2, IGFBP3, IGFBP7, APC and PTGS2." (PMID 33076494, 2020). "GSTP1 is commonly inactivated by somatic CpG island hypermethylation in cancers of the prostate, liver, and breast." (PMID 33615312, 2020). "By contrast, GSTP1 has been reported to possess pro-oncogenic activity that protects cancer cells from apoptosis signals by suppressing MAPK/JNK kinase signaling." (PMID 33202946, 2020). "To further examine the effects of NQO1 and GSTP1 on U87MG/EGFRvIII cancer cell proliferation in vivo, we constructed stable knockdown cell lines that expressed their specific shRNAs." (PMID 33087132, 2020). "Given GSTP1’s cytoprotective roles in xenobiotic detoxification, chemotherapeutics, and modulating oxidative stress, GSTP1 inhibitors emerged as promising anti-cancer compounds and have been used alone or in combination with chemotherapeutic drugs." (PMID 32526885, 2020).
cancer (continued). "The main objective of this study was to determine the efficacy of T. indica extract on cancer inhibition either alone or with traditional chemotherapy dependent on the inhibition of human GSTP1-1 and oxidative status." (PMID 33215267, 2020). "The expression levels of mRNA of the resistance genes, like GSTP1, were measured in cancer tissue specimens and compared with pathological data, to understand their role in primary drug resistance." (PMID 31357662, 2019). "In cancer research, the study of structural biology, enzymology, and drug development remain extremely important mainly to inhibit the over-expressed GSTP1-1 and modulate its pro-apoptotic activity." (PMID 31357662, 2019). "Subgroup meta-analysis by geographical populations revealed that GSTP1 methylation was significantly higher in HBV-positive carcinoma tissues in China and Japan." (PMID 31772678, 2019). "This meta-analysis showed that methylation of GSTP1 gene in HBV-positive carcinoma tissues was significantly higher than in HBV-negative carcinoma tissues, and the same consequence was also found in adjacent tissues." (PMID 31772678, 2019). "Given these points, GSTP1 appears to play a driving role in multistep cancer development through a number of varying mechanisms and pathways." (PMID 30043549, 2018). "GST isoenzymes such as GSTP1-1 are overexpressed in many cancer cell lines and can induce drug resistance." (PMID 29358310, 2018). "Being predominantly overexpressed GST isoenzyme in cancer cells, GSTP1 plays a significant role in resistance to chemotherapy as confirmed in pre-clinical data from cancer cell lines, but also in cancer patients." (PMID 30487385, 2018). "Namely, its upregulated expression has been related to worse chemotherapeutic response to anti-cancer drugs such as cisplatin and chlorambucil, recognized as GSTP1 substrates." (PMID 30487385, 2018). "The human GSTP1 gene is located on chromosome 11 (11q13.2), and the GSTP1 (Glutathione S-Transferase pi) protein participates in the drug resistance process of cancer cells." (PMID 30740061, 2018). "As already mentioned, GSTP1-1 is over-expressed in several cancers where it protects cells from cell death by inhibiting the activity of JNK or its upstream activation." (PMID 29362397, 2018). "In comparison with normal tissues, variability of GSTP1 levels was described in different human cancers." (PMID 30043549, 2018). "6-(7-nitro-2,1,3-benzoxadiazol-4-ylthio)hexanol (NBDHEX) is a highly efficient inhibitor of GSTP1-1 and other GSTs, which triggers apoptosis in several cancer cells 96,97." (PMID 29362397, 2018). "Previous reports indicated that the interaction of GSTP1 with the viral oncoprotein E7 from HPV16 provides the cancer cells with a better adaptation capacity under stress." (PMID 29774096, 2018). "Among samples with low‐grade cancer, 33.33% of cases (4/12) exhibited strong GSTP1 expression, 58.33% of them (7/12) showed moderate expression, while 8.33% (1/12) had weak GSTP1 expression." (PMID 30043549, 2018). "Microsomal GST1 (MGST1) and GSTP1-1, which are frequently overexpressed in cancer cells, contribute to DOX resistance." (PMID 29362397, 2018). "Glutathione-S-transferase P1 (GSTP1) is an important phase II enzyme that can protect cells from oxidative stress in various human cancers." (PMID 27965466, 2017). "GSTP1 has been considered as a marker for cancer development, disease progression as well as drug resistance." (PMID 28254657, 2017). "In contrast, SOD2 and GSTP1 are downregulated in the cancer cell lines secretome, according to the proteomic analysis." (PMID 28261610, 2017). "Human GSTP1 has also recently attracted attention as a cancer marker due to its presence in many cancer cells, and correlation with malignancy and treatment resistance has been reported." (PMID 28859615, 2017). "Among the 4 GST isozymes, glutanthione S-transferase-p1 (GSTP1) has been reported to play an important role in the resistance of cancer cells to alkylating agents." (PMID 29116019, 2017).
cancer (continued). "On the other hand, the SNP in GSTP1 gene resulting in amino acid substitutions at codon 105 (Ile→Val) is also associated with reduced detoxifying activity of the GST enzyme and cancer risk but less studied in premalignant gastric lesions." (PMID 28182092, 2017). "Based on that, inhibitors of GSTP1-1 are expected to counteract drug resistance and serve as adjuvants in cancer chemotherapy by increasing efficacy." (PMID 27487128, 2016). "The AUCs ranged from 0.85 (PTGS2) to 0.99 (GSTP1), confirming cancer-specific methylation, with GSTP1 methylation as the best classifier." (PMID 26086362, 2015). "If we inhibit expression of NCK1 or GSTP1 in cancer, we can expect their target gene expression to be similar to the control." (PMID 26336805, 2015). "Over-expression of the GSTP1 gene was observed in several cancer types and is considered to be a marker for cancer development." (PMID 25945082, 2015). "Glutathione S-transferases, GSTs, are important for the detoxification of electrophilic metabolites of carcinogens and reactive oxygen species, and genetic and epigenetic variation particularly in GSTP1 has been the focus of much research in different cancers." (PMID 26393654, 2015). "GSTP1 is widely distributed and has previously been shown to be increased in many cancer types and is the most predominantly expressed GST isozyme in the NCI-60 cancer cell line panel." (PMID 26569310, 2015). "The epigenetic silencing of GSTP1 provides a mechanism of resistance which makes tumors with GSTP1 promoter methylation bad candidates for the GST-activated anti-cancer prodrugs presented in this review." (PMID 25157234, 2014). "This gene codes for the glutathione S-transferase Pi-1, an enzyme involved in cellular detoxification of xenobiotics and carcinogens, being a promising biomarker for cancer diagnosis and prognosis." (PMID 24271385, 2014). "Ethacrynic acid, a diuretic, has been shown to counter GSTP1-1 activity and, hence, it can be used in chemotherapy to increase the effectiveness of alkylating cancer drugs." (PMID 24575413, 2014). "PL directly binds to and inhibits the antioxidant enzyme glutathione S-transferase pi 1 (GSTP1), resulting in elevated levels of ROS and subsequent cancer-selective cell death." (PMID 24967005, 2014). "As an example, Canfosfamide (TLK286, TELCYTA®), a cancer cell-activated prodrug, was designed to exploit the elevated levels and the activity of glutathione S-transferase P1-1 (GSTP1-1) that is overexpressed in many human cancer cells." (PMID 25191271, 2014). "As such GSTP1 methylation patterns allow distinguishing two groups: one benign unmethylated group as well as samples presenting hypermethylated GSTP1 gene promoters in the borderline/malignant tumor group." (PMID 25076909, 2014). "Promoter methylation of several cancer-related genes (e.g., GSTP1, APC, RARB2, and RASSF1A) has been extensively documented in PCa and seems to occur early in prostate carcinogenesis, as demonstrated by its intermediate frequency in HGPIN lesions." (PMID 24344919, 2013). "The calculation of GSTP1 hypermethylation can accurately detect the presence of cancer even in small, limited tissue samples." (PMID 24282788, 2013). "GSTP1-1 activity and P-gp levels were often found higher in the chemotherapy-resistant cancer cell lines, such as the B-MD-C1 cell line treated with Adriamycin compared to the sensitive cells." (PMID 24058374, 2013). "GSTP1 has also been postulated in several cancer types to enhance the metastatic potential and the development of resistance to drugs that induce reactive oxygen species (ROS), such as paclitaxel and cisplatin." (PMID 23671674, 2013). "The study of mutations in GSTP1 and NAT2 genes is necessary in assessing the risk of the development of various diseases, such as cancer." (PMID 29805847, 2013). "The GST superfamily, particularly the P1-class GST (GSTP1-1), is frequently overexpressed in various human cancers." (PMID 24058374, 2013).